ANKAR (ankyrin and armadillo repeat containing)
Synonyms: FLJ25415
Tractability: Antibody: UniProt predicts a signal peptide or a membrane-spanning region.
Gene: Protein-coding gene on chromosome 2 (189,674,290 to 189,761,193, forward strand). Ensembl gene ENSG00000151687.
Subcellular location: Membrane
Subcellular location (Human Protein Atlas): Centriolar satellite; Nucleoplasm
Gene Ontology:
Cellular component: membrane
Genetic constraint (gnomAD): Loss-of-function variants: 106 observed, 116.38 expected, observed/expected ratio (o/e) 0.91, 90% interval 0.78 to 1.07. The upper end of that interval is the gene's LOEUF score, 1.07, which puts it in group 4 of 6, group 1 being the genes least tolerant of losing a copy. Missense variants: 1,331 observed, 1,463.2 expected, observed/expected ratio (o/e) 0.91, 90% interval 0.87 to 0.95. Synonymous variants: 434 observed, 510.17 expected, observed/expected ratio (o/e) 0.85, 90% interval 0.79 to 0.92.
Homologues: Orthologues: chimpanzee ANKAR (99% identical), macaque ANKAR (98% identical), pig ANKAR (90% identical), rabbit ANKAR (87% identical), dog ANKAR (87% identical), rat Ankar (85% identical), guinea pig ANKAR (83% identical), mouse Ankar (82% identical), tropical clawed frog ankar (52% identical), zebrafish ankar (47% identical), Drosophila melanogaster arm (8% identical), Caenorhabditis elegans hmp-2 (5% identical). Paralogues in human: ARMC3 (11% identical), ODAD2 (10% identical), CTNNB1 (8% identical), JUP (8% identical).
Diseases named in the same sentence as ANKAR in open-access papers:
ANKAR is named in the same sentence as 5 diseases in open-access papers, as found by Europe PMC text mining. Sharing a sentence is not in itself a finding about the gene and the disease. The quoted sentences say what the papers report.
metastatic disease (2 papers, 2024). "In particular, PSMB4, RUVBL2, and ANKAR EV protein levels were increased in patients with metastatic disease, whereas RAP2B, SERPINA12, and IGLV4-69 abundance levels were decreased in the cEVs of patients with metastasis." (PMID 39693144, 2024). "In particular, PSMB4, RUVBL2 and ANKAR EV protein levels were increased, whereas RAP2B, SERPINA12 and IGLV4-69 abundance levels were decreased in the cEVs of patients with metastatic disease." (PMID 36993200, 2024).
endometrial cancer (1 paper, 2020). Primary or metastatic malignant neoplasm involving the endometrium (mucous membrane that lines the endometrial cavity). "A third smaller, but distinctly separate, network of IL13, IL21, ANKAR, CAPS, and IGFALS was associated with Wnt and VEGF signaling, and are likely associated with environmental cues in high-grade endometrial cancer." (PMID 32471032, 2020).
Hypercholesterolemia (1 paper, 2013). An increased concentration of cholesterol in the blood. "Of the DEGs in the that were up-regulated in common between the hypertension only- and hypercholesterolemia plus sham groups (both vs. sham controls), Nibrin like (LOC100352398) showed the largest fold change, followed by TAF15, and ANKAR." (PMID 23874591, 2013).
Hypertension (1 paper, 2013). The presence of chronic increased pressure in the systemic arterial system. "Among the highly up-regulated genes in the MCA of the hypertension only group compared to sham controls were Nibrin like (LOC100352398), TAF15 and ANKAR." (PMID 23874591, 2013).
tumor (1 paper, 2022). "The tumor-associated significance of the other seven genes (HIST2H2AA4, UQCRHL, AC008269.1, RAB6D, APOL4, HIST1H2AI, ANKAR, SGMS1) remains unclear." (PMID 35480120, 2022).